PPARA (peroxisome proliferator activated receptor alpha)
Diseases named in the same sentence as PPARA in open-access papers (continued):
Sharing a sentence is not in itself a finding about the gene and the disease.
Obesity (continued). "Therefore, fenofibrate-activated PPARα is suggested to be involved in the regulation of obesity-induced insulin resistance." (PMID 37935669, 2023). "In this aspect, PPARα activation is beneficial to glucose homeostasis through control of obesity." (PMID 36589809, 2022). "Also, animal trials have demonstrated that increased dietary BCAA improved glucose and lipid metabolism by upregulating the expression of peroxisome proliferator-activated receptor-alpha to prevent diet-induced obesity in mice models." (PMID 35382800, 2022). "L. plantarum FRT10 alleviated obesity in mice by activating the PPARα/CPT1α pathway." (PMID 35721808, 2022). "In this study, we demonstrated that Torularhodin has an anti-obesity and anti-hepatic dyslipidemia effect through regulating the expression of the PPARα signaling pathway-related proteins to increase fat degradation and cholesterol execration accompanying reduced lipid absorption." (PMID 36234935, 2022). "Besides cholestasis, PPARα is also involved in the treatment of obesity-related diseases, such as atherosclerosis and non-alcoholic fatty liver disease." (PMID 35370715, 2022). "On the contrary, activation of PPARα and β is found to reduce obesity and improve dyslipidemia." (PMID 36172518, 2022). "In the model of HFD-induced obesity, PPARα activation and GLP-1 stabilization resulted in decreased endotoxemia, which could be explained by the lower intestinal permeability to LPS." (PMID 36430628, 2022). "This may explain why DCHT is considered as a treatment of obesity and hyperlipidemia, since PPARα plays a central role in the onset and progression of these diseases." (PMID 35370715, 2022). "(-)-Epigallocatechin-3-gallate (EGCG), a green tea catechin, exhibited PPARα and PPARγ agonist properties in subcutaneous adipose tissues, but PPARγ antagonist activity in epididymal adipose tissue to reduce obesity and epididymal white adipose tissue weight in HFD mice via activation of AMPK." (PMID 36092543, 2022). "Additionally, a study indicates that PPARα increases adiponectin secretion that leads to increased hepatic fatty acid oxidation, which inhibits obesity-induced fatty liver." (PMID 35163298, 2022). "Since Nisch regulates the expression of ACSL3, PPARα, and CHREBP, activation of PPARα/AMPK expression of Nisch may be a novel approach to inhibit obesity and hepatic steatosis, and thus, Nisch may play an important role in obesity." (PMID 35163298, 2022). "Recent research has established that apigenin is a PPAR modulator that inhibits obesity-induced metabolic syndrome via suppressing PPARγ and PPARα, resulting in activation/inhibition of upstream or downstream targets, such as STAT3, C/EBP-α, SREBP-1c, CD36, and Nrf2 in adipose tissues." (PMID 36092543, 2022). "High hepatic expression of FXR protected against hepatic steatosis and elevated TG through the induction of lipolytic target genes in mice, while TGR5 activated PPARA to increase mitochondrial oxidative phosphorylation and energy metabolism, as well as reduce obesity in humans." (PMID 35145986, 2022). "Of note however, pharmacologic PPARα activators reduced adiposity in mouse models of obesity." (PMID 35204243, 2022). "The PPARα agonist fenofibrate has been shown to improve the vascular stiffness in obesity patients." (PMID 36552585, 2022). "Interestingly, the phenotype of RIP140 knockout mice suggests a role for this corepressor in PPARα signaling, as these mice exhibit resistance to high-fat diet-induced obesity, resulting from the upregulation of genes involved in energy dissipation." (PMID 34445672, 2021). "On the other hand, obesity could be a stimulator of the peroxisome proliferator-activated receptor PPARα/δ target genes in NK cells that encourage the NK cells to further accumulate more lipids and hence hinder the cytotoxicity of NK cells." (PMID 34212054, 2021).
Obesity (continued). "PPARα expression is also decreased in the WAT of mice with genetically or HFD-induced obesity, and PPARα agonists can reduce adiposity and improve insulin resistance in such obese mouse models by stimulating both differentiation and fatty acid oxidation in adipocytes." (PMID 34445679, 2021). "In this study, we speculated that the relationship between the reduced expression of Tets and the increased methylation level of Pparα may have started during gestation, thereby leading to lipid metabolism disorders and obesity in offspring later in life." (PMID 33955677, 2021). "PPARα pharmacological intervention could be used to fight obesity by preventing beige-to-white transition." (PMID 34638914, 2021). "Therefore, we established the first adipose-specific PPARα knockout (PparaFatKO) mice to determine the signaling position of PPARα in adipose tissue expansion that occurs during the development of obesity." (PMID 35011564, 2021). "Although strategies targeting CB1R/PPARα have been explored in further depth for the treatment of obesity, the concomitant modulation of CB1R and PPARγ may also be useful for the control of metabolic syndrome and related disorders." (PMID 33498245, 2021). "We speculated that the hypermethylation of Pparα resulted from the decreased Tet1/2 expression in mothers given a HFD during gestation, thereby causing lipid metabolism disorders and obesity." (PMID 33955677, 2021). "Given that miR‐22 directly targets genes such as Pgc‐1α, PPARα, and Sirt1, which are involved in the control of metabolism and obesity, it would be highly valuable to investigate whether miR‐22 may contribute to metabolic alterations induced by obesity." (PMID 33159388, 2021). "Therefore, VS extract effectively diminished obesity and hyperglycemia by suppressing C/EBPα-mediated lipogenesis in the AT and liver, enhancing PPARα-mediated fatty acid β-oxidation in muscle, and PPARγ-mediated insulin sensitivity in AT and muscle." (PMID 33671428, 2021). "In the present study, the administration of a HFD during pregnancy led to decreased expression of Pparα in foetal livers, possibly by inhibiting the demethylation of Pparα‐dependent fatty acid oxidation–related genes and ultimately inhibiting lipid catabolism and inducing obesity." (PMID 33955677, 2021). "Several potential obesity candidate genes and variants have been documented, including LEP and LEPR, which have been mainly implicated in monogenic obesity, as well as FTO, APOE, PPARG, and PPARA which have been mainly implicated in polygenic/common obesity." (PMID 34131278, 2021). "Moreover, PPARα activation has shown to play a therapeutic role in the regulation of lipid metabolism and obesity." (PMID 33498245, 2021). "However, the physiological level of bilirubin seems to be beneficial for preventing obesity and diabetes because bilirubin directly binds with peroxisome proliferator-activated receptor alpha (PPARα), and positively drive the fatty acid β-oxidation." (PMID 32296105, 2020). "PPARα also contributes to the elevations in myocardial fatty acid uptake and subsequent lipotoxicity observed in obesity/T2D, which may be dependent on increased glycogen synthase kinase 3α (GSK3α) activity." (PMID 33041869, 2020). "Given that IAAs exhibit both anti-obesity and anti-diabetic effects via activation of PPARα and PPARγ, IAAs were hypothesized to markedly prevent obesity-induced cognitive decline." (PMID 31940997, 2020). "It is reported that PPARα exhibits inflammation-suppressing effects in obesity, atherosclerosis, autosomal dominant polycystic kidney disease, and acute kidney injury, but the role of PPARα in inflammation in NP still remains unclear." (PMID 33414819, 2020). "Likewise, studies on mice with induced obesity, exhibited reduced expression of PPARα and carnitine palmitoyltransferase I (CPT-1) in the liver." (PMID 33292260, 2020).
Obesity (continued). "However, telmisartan also induces anti-fibrotic and anti-obesity effects through PPARδ-dependent pathways and enacts anti-hepatic fibrosis and anti-dyslipidemic effects through PPARα-dependent pathways." (PMID 30850637, 2019). "The expression of PPARα is generally decreased in HFD-induced obesity." (PMID 31336903, 2019). "Therefore, PPARα activators hold full promise as therapy for patients with obesity and type 2 diabetes, but also for subjects with severe liver conditions, such as NAFLD." (PMID 31489930, 2019). "We showed that spilanthol significantly inhibits the adipogenic proteins C/EBPα, C/EBPβ, PPARα, PPARγ, and SREBP-1 in the liver, and that spilanthol has notable effects against obesity and associated metabolic abnormalities, such as insulin resistance and hyperlipidemia." (PMID 31052312, 2019). "The thermogenic functions in the iWAT and BAT of mice treated with pemafibrate were increased via increased hepatic FGF21 production and the direct effects of pemafibrate on PPARα in peripheral tissues, leading to the amelioration of obesity-induced dysfunction." (PMID 30041488, 2018). "In addition, treatment with PPARα agonists in animal models of obesity attenuates adiposity and adipocyte hypertrophy and improves glucose metabolism defects, such as hyperglycemia, glucose intolerance and insulin resistance." (PMID 30041488, 2018). "Reduced DNA methylation is associated with enhanced induction of hepatic FGF21 expression after PPARα activation, which may partly explain the attenuation of diet-induced obesity in adulthood." (PMID 29434210, 2018). "A recent study had further explored that APN could protect obesity or diabetes-induced NAFLD via activating AdipoRs/PPARα signaling pathway." (PMID 30473540, 2018). "PPARα and PPARβ/δ are potential targets to prevent obesity, by the mechanism in Section 2.1." (PMID 29690611, 2018). "Because of PPARα agonists’ prooxidative actions, activators of this nuclear hormone receptor may be used to improve obesity-induced insulin resistance." (PMID 30037087, 2018). "The PPARα agonist–FGF21–WAT interaction may contribute to the anti-obesity effect of PPARα agonists." (PMID 30041488, 2018). "Thus, it represents another candidate PPARα/γ agonist to enhance many metabolic profiles in obesity-related diseases." (PMID 30079233, 2018). "Also 5-caffeoylquinic acid improved obesity and fatty liver through the amelioration of lipid metabolism by PPARα activation and LXRα inhibition." (PMID 29201040, 2017). "In addition, PPARs (peroxisome-proliferator-activated receptors) are the nuclear hormone receptor including PPARα, PPARδ, and PPARγ, which play a critical role in regulation of obesity, cardiovascular diseases, and inflammation." (PMID 28293264, 2017). "Furthermore, its involvement in obesity resistance through regulation of metabolic genes such as PPARA and UCP1 highlight a transcriptional network focused on lipid modifiers." (PMID 28416760, 2017). "Certain compounds under development have dual PPARα/γ agonistic activity which might be beneficial in obesity and diabetic cardiomyopathy." (PMID 28656106, 2017). "Thus it appears that PPARα is integral for the metabolic adaptations/maladaptations (increased ketogenesis and gluconeogenesis) in response to either fasting or obesity-induced lipid accumulation." (PMID 27708682, 2016). "In terms of prevention of obesity, isomerized hop extract, which consists primarily of iso-α-acids, was shown to prevent diet-induced obesity by the modulation of lipid oxidation in the liver via PPARα activation and inhibition of intestinal lipid absorption." (PMID 26098641, 2015). "SIRT1, an NAD+ dependent type III deacetylase sirtuin, enhances glucose tolerance by potentiating brown adipose tissue function contributing to energy expenditure and browning of WAT and resistance to dietary obesity, interacts with PPARα and is required to activate PGC-1α." (PMID 26834634, 2015).
Obesity (continued). "However, Stienstra and colleagues suggested that IL-1β-mediated suppression of hepatic PPARα and fatty acid oxidation was responsible for hepatic lipid accumulation in obesity." (PMID 25216251, 2014). "Moreover, we have previously demonstrated that exposure to maternal obesity leads to reduced mRNA expression of PPARα target genes prior to the development of obesity or adiposity gains." (PMID 24416203, 2014). "Mice overexpressing PPARα in skeletal muscle exhibit glucose intolerance but are protected from high fat diet (HFD)-induced obesity, while PPARα null mice exhibit enhanced glucose tolerance, despite increased triacylglycerol accumulation in muscle and HFD-induced obesity." (PMID 24619218, 2014). "Our findings indicated that offspring from obese rat dams have detrimental alternations to circadian machinery that may contribute to impaired liver metabolism in response to HFD, specifically via reduced PPARα expression prior to obesity development." (PMID 24416203, 2014). "Consequently, via ChIP, we assessed if maternal obesity and HFD led to differences in histone demarcation (H3K4me3 and H3K27me3) on the PPARα promoter that were associated with changes in gene expression." (PMID 24416203, 2014). "Accordingly, ChIP was performed on the PPARα promoter to assess whether the effects of maternal obesity and HFD on PPARα mRNA expression were related to epigenetic changes, specifically histone modifications." (PMID 24416203, 2014). "In murine models of diet induced obesity, PPARα expression has been show to increase." (PMID 24818992, 2014). "The impact of the pharmacological activation of mouse PPARα in the context of obesity-induced hepatic inflammation is also reviewed as well as the potential relevance of PPARβ/δ as a molecular drug target to fight liver inflammation in the case of nonalcoholic fatty liver disease." (PMID 23766760, 2013). "Moreover, PPARα activators have been shown to regulate obesity in rodents by both increasing hepatic fatty acid oxidation and decreasing levels of circulating triglycerides responsible for adipose cell hypertrophy and hyperplasia." (PMID 23762402, 2013). "Therefore, the potential therapeutic usefulness of PPARα and PPARγ activation in the control of obesity and diabetes-induced chronic (low-grade) inflammation has extensively been studied over the last couple of years using rodents." (PMID 23766760, 2013). "Since endurance exercise causes activation of PPARα, these data suggest that endurance exercise was able to restore at least in part the obesity-induced disruption of PPARα function and thereby contributed to the elevated gene expression of OCTN2, ALDH9A1, and BBOX1." (PMID 23150726, 2012). "Recent evidence suggests that activation of CNS PPARα and/or PPARγ may contribute to weight gain and obesity." (PMID 22916190, 2012). "Due to their involvement in TG re-synthesis and secretion, it is believed that MOGAT2 and 3, but also DGAT1 are potential therapeutic drug targets for treating diet-induced dyslipidemia and obesity, whereas an activation of PPARα was suggested as the initial regulator." (PMID 23241455, 2012). "The identification of PPARs as key regulators of diverse aspects of energy homeostasis has made them attractive pharmacological targets to treat metabolic diseases such as lipid disorders (drugs targeting PPARα or -δ), T2D (drugs targeting PPARγ), and obesity (drugs targeting PPARδ)." (PMID 22745632, 2012). "Recent evidence suggests that CNS activation of PPARα and/or PPARγ may contribute to weight gain and obesity." (PMID 22916190, 2012). "In conclusion, in vivo and in vitro studies demonstrate that E2 inhibits the actions of PPARα on obesity through its effects on hepatic PPARα -dependent regulation of target genes and that these processes are mediated by inhibition of PPARα recruitment of coactivators by E2-activated ERs." (PMID 20871824, 2010).
Obesity (continued). "PPARα is abundantly expressed in liver, brown adipose tissue, kidney, intestine, heart, and skeletal muscle; and its ligands have been used to treat diseases such as obesity and diabetes." (PMID 18725983, 2008). "Following thepublication of several high-profile studies implicating PPARδ as a potential target for obesity andassociated metabolic disorders, multiple pharmaceutical companies haveinitiated drug discovery efforts to identify specific PPARδ, PPARα/δ, PPARγ/δ, and pan PPAR modulators." (PMID 18989368, 2008). "Since synthetic PPARα and PPARγ agonistsindependently ameliorate obesity-induced inflammation, agoniststhat activate both PPARα and PPARγ (the so-calleddual PPARα/PPARγ agonists) might be even moreeffective." (PMID 17389767, 2007). "These activities impinge directly on thecontribution of PPARα to obesity." (PMID 17389768, 2007). "The network shows that RXRA interacts with proteins related to a tumor (THRA related to pituitary adenome) and those related to certain diseases caused by abnormalities in lipid metabolism (e.g., NR0B2 related to obesity, PPARA to hyperapobetalipoproteinemia, and PPARGC1A to lipodystrophy)." (PMID 17705877, 2007). "The effects of PEG400 on PPARα signaling may explain its role in mitigating obesity." (PMID 40004195, 2025). "Furthermore, because blood pressure is elevated in mice with liver-specific knockout of PPARα, the activation of PPARα by hexaraphane in the liver may also contribute to the attenuation of obesity-induced blood pressure elevation." (PMID 40507037, 2025). "Adipose Tissue and Metabolic Effects: SGLT2is mitigate obesity-associated adiposopathy by shifting macrophage polarization (M1 to M2), reducing proinflammatory cytokines (TNF-α, IL-6), and enhancing adipose tissue browning (UCP1 upregulation) and mitochondrial biogenesis (via PGC-1α/PPARα)." (PMID 40863154, 2025). "PUFAs may benefit MAFLD by improving obesity and insulin resistance, mainly by modulating gene expression of peroxisome proliferator-activated receptor alpha (PPARα), sterol regulatory element binding protein-1 (SREBP-1), and carbohydrate regulatory element binding protein (ChREBP)." (PMID 40292496, 2025). "It is these effects that cause obesity-induced thermogenesis: in BAT and inguinal WAT, β3AR signaling induces PRDM16 and PGC1α via the β3AR–cAMP–PKA pathway and increases UCP1 expression in mice; PPARα and PPARγ are also involved in heat production through this signaling pathway." (PMID 39796158, 2024). "Furthermore, a recent discovery of a hormonal function of bilirubin has shown the ability of bilirubin to bind directly to peroxisome proliferator-activated receptor alpha (PPARα) that induces gene responses which eventually lead to improvement in insulin resistance and obesity." (PMID 38468265, 2024). "Importantly, recent studies suggest that the activation of PPARα may provide protective effects in obesity-related kidney injury by promoting the utilization of FFAs and attenuating inflammation." (PMID 39765868, 2024). "However, it is acknowledged that while the PPARα to a lesser degree, and PPARγ in particular are key coordinators in the adipogenesis metabolic axis, this is not the entire mechanistic picture towards adverse adipogenicity leading to obesity." (PMID 39040675, 2024). "Obesity and dietary fat intake are known to increase this rate‐limiting enzyme and a protein phosphatase that inhibits peroxisome proliferator‐activated receptor (PPARα)‐mediated transcription of fatty acid oxidation‐related genes and fatty acid oxidation in mitochondria." (PMID 39725655, 2024). "Moreover, PPARα is closely related to obesity and insulin resistance." (PMID 37305395, 2023). "Thus, the overexpression of AdipoR1 in the liver of a mouse model of human obesity caused an increase in the activation of the AMPK pathway, while the overexpression of AdipoR2 caused an increase in the expression of peroxisome proliferator activated receptor alpha (PPAR-α) target genes." (PMID 34860303, 2022).